SENP3 (SUMO specific peptidase 3)
Diseases named in the same sentence as SENP3 in open-access papers (continued):
Sharing a sentence is not in itself a finding about the gene and the disease.
cancer (26 papers, 2012 to 2025). A tumor composed of atypical neoplastic, often pleomorphic cells that invade other tissues. "Dysregulation of SENP3 has been linked to many human diseases including cancer, heart disease, and neurological disorders, yet very little is known about what regulates SENP3’s SUMO protease activity." (PMID 40712028, 2025). "SENP3 overexpression in cancer cells causes improper desumoylation of specific proteins, which impairs their function." (PMID 35887358, 2022). "Two important processes, the dysregulation of which is tightly associated with cancer, are under the control of SENP3: mitosis and DDR." (PMID 35887358, 2022). "To further explore whether SENP3 loss in macrophages is associated with cancer metastasis, we established a metastatic mouse model by injecting Luc‐Py8119 cells through the tail vein." (PMID 33932085, 2022). "Therefore, we tested if the parallel association between Sp1 and SENP3 levels in an in vitro cell system reflects the situation in cancer cells and patient-derived tissues." (PMID 26511642, 2016). "We examined whether the levels of SENP3 are linked to the carcinoma development among patients." (PMID 35356800, 2022). "Exactly, previous studies have shown that PRPF8, SPAG7, SENP3 and GPS2 are associated with the occurrence of various cancers." (PMID 40015977, 2025). "To investigate the influence of SENP3 on cancer hallmarks, including proliferation, invasion and resistance to apoptosis, we conducted a number of in vitro functional experiments." (PMID 39755756, 2025). "The results indicate that SENP3 reduces the expression of E-cadherin in PCa cells, increases the expression of N-cadherin, thereby facilitating the invasion and dissemination of cancer cells." (PMID 39623295, 2024). "Sentrin/SUMO-specific protease 3 (SENP3) is essential to regulate protein stability and function in normal and cancer cells." (PMID 39623295, 2024). "Previous studies demonstrate that SENP3, a redox-sensitive SUMO2/3-specific protease, is strongly implicated in the development and progression of cancer and cardiovascular diseases." (PMID 38070059, 2023). "SENP3 has been demonstrated to play important roles in the development and progression of cancer and cardiovascular diseases, which was mediated by its de-SUMOylation of various protein substrates." (PMID 38070059, 2023). "Meanwhile, we observed a similar effect of SENP3–9A on innate immune response in human cancer cell line U2OS cells." (PMID 35869062, 2022). "This also correlated with the observation of prevalent amplification and deletion of the SENP7 and SENP3 genomic loci, respectively, in most cancer types." (PMID 35887358, 2022). "A dramatic increase was observed in the apoptosis percentage of cancer cells with SENP3 knockdown after being treated with irradiation." (PMID 35356800, 2022). "Upon knocking down SENP3, cancer cells became strongly sensitive to DNA damaging drugs and irradiation." (PMID 35356800, 2022). "The induction of SENP3 in cancer cells initiates the angiogenic pathway; specifically SENP3 regulates the transcriptional activity of hypoxia-inducible factor 1α (HIF1α) via desumoylation of the co-regulatory protein p300." (PMID 27178176, 2016). "Increased SENP3 regulates the functions of the substrates in cancer cells through reversal of SUMO2/3 modification, which leads to the enhanced cell proliferation, tumorigenesis and angiogenesis." (PMID 25216525, 2014). "Moreover, the levels of downstream molecules (including p-eIF4E, cyclin D1, snail, and Bcl2) regulated by RACK1 were also decreased after SENP3 knockdown, which is consistent with the impact of SENP3 on cancer hallmarks." (PMID 39755756, 2025). "Last, our crystal structure could aid in structural based design of SENP3-specific protease inhibitors, which may have therapeutic potential for cancer therapy." (PMID 40712028, 2025).
cancer (continued). "SENP3 is a cancer-promoting protein, which up-regulates protein level of STAT3." (PMID 36227136, 2022). "Our previous studies have demonstrated that the SENP3 rapidly (within 1 h) increases its own level through a redox-sensitive stabilization under oxidative stress conditions and remains accumulated in many types of human cancer tissues." (PMID 26511642, 2016). "We next used two nude mouse models to assess the role of SENP3 in cancer cell metastasis in vivo." (PMID 25216525, 2014). "Hence, the induction of SENP3 directly contributes to cancer progression, providing another attractive alternative target for therapy, possibly most notably in cancers with increased ROS levels, including PCa." (PMID 24970135, 2012). "NRF2 promotes cell protection against oxidative stress, chemotherapy and radiotherapy, and it has been observed that cisplatin-induced ROS generation triggers intranuclear activation of NRF2 via SENP3 activity, which may be related to diminished cancer cell responses to chemotherapy." (PMID 35887358, 2022). "We test whether silencing STAT3 reverses the cancer-promoting effect of SENP3." (PMID 36227136, 2022). "Both SENP3 and Sp1 may over-accumulate in certain types of human cancers." (PMID 26511642, 2016). "Therefore, a profound change in global protein turnover could be predicted following the increase of SENP3 under oxidative stress-related physiological and pathological scenarios including cancers." (PMID 26511642, 2016). "SENP3 is accumulated in a number of primary human malignancies, which includes ovarian, lung and CRC cancers, and in this latter, PML appears hypo-sumoylated." (PMID 35887358, 2022). "Overexpressed SENP3 leads to the imbalance of SUMO homeostasis and to development and progression of a number of cancers including prostate, ovarian, lung, rectum, and colon." (PMID 31318878, 2019). "SENP3, a SUMO2/3‐specific protease, is closely involved in the development of cancer." (PMID 40019399, 2025). "Our findings provide a new explanation for the enrichment of Sp1 protein in cancers and suggest a global regulation of SUMO2/3 conjugated proteins whose levels may be tightly controlled by SENP3 and RNF4." (PMID 26511642, 2016). "Our previous study shows that SENP3, a redox-sensitive SUMO2/3-specific protease, accumulates in a variety of cancers, but whether SENP3 and SUMOylation involve in the regulation of EMT is unclear." (PMID 25216525, 2014). "SENP3, as a nucleolar protein, preferentially, nevertheless not exclusively, interacts with nuclear proteins, and has increased levels in various cancer tissues." (PMID 26511642, 2016).
infection (12 papers, 2019 to 2025). The state of being infected such as from the introduction of a foreign agent such as serum, vaccine, antigenic substance or organism. "SENP3 overexpression promoted the ACE2 degradation, whereas the protein abundances of ACE2 and the infection of SARS-CoV-2 were increased by SENP3 deficiency." (PMID 36057605, 2022). "NyxA and NyxB have been shown to interact with the host deSUMOylase SENP3 and mediate its delocalization from the nucleoli when ectopically expressed and during infection." (PMID 40395090, 2025). "We found that NyxA and NyxB can be part of the same complex in cells and that their dimer conformation is essential for SENP3 recruitment during infection." (PMID 40395090, 2025). "After 48‐h postinfection, expression of the monomeric versions of NyxA and NyxB did not complement the respective deletion phenotypes, confirming Nyx dimerization is essential for SENP3 delocalization during infection." (PMID 40395090, 2025). "The translocated Nyx effectors directly interact with SENP3 via a defined acidic patch (identified from the crystal structure of NyxB), preventing nucleolar localisation of SENP3 at late stages of infection." (PMID 36609656, 2023). "Here we report the identification of two Brucella effectors that target SENP3 and induce its delocalisation from the nucleoli during infection." (PMID 36609656, 2023). "The depletion of SENP3 resulted in a substantial rise in cytoplasmic NVL-positive Bif being formed as early as 24 h post-infection." (PMID 36609656, 2023). "Alternatively, prolonged siRNA depletion of SENP3 from the early stages of the infection to 48 h post-infection indirectly impacts Brucella replication, for example, by decreasing ribosomal biogenesis and host protein synthesis." (PMID 36609656, 2023). "In this study, we identify two translocated effectors, NyxA and NyxB, that interact with SENP3, leading to its subnuclear mislocalisation during infection." (PMID 36609656, 2023). "As SENP3 seems to be the host target of both Nyx effectors, we determined its relevance during infection." (PMID 36609656, 2023). "We next treated the cells with SARS-CoV-2 S pseudotyped virus, finding that SENP3 depletion dramatically enhanced the infection of SARS-CoV-2 S pseudotyped virus by luciferase assay." (PMID 36057605, 2022). "In the scrambled shRNA control condition, 30 min ischemia reduced cytosolic SENP3 by 50%, about the same reduction as achieved by infection with SENP3 shRNA." (PMID 30973885, 2019). "RT-qPCR and immunoblotting showed that SENP3 decreased significantly in HepG2-NTCP cells after HBV infection compared with HepG2-NTCP cells that had mock infection as control." (PMID 30640896, 2019). "SENP3 delocalization was used as a measure of Nyx function during infection." (PMID 40395090, 2025). "Therefore, we conclude that NyxA and NyxB are likely part of the same complex in infected cells, responsible for the SENP3 delocalization observed at late stages of the infection." (PMID 40395090, 2025). "Therefore, in the late stages of the infection, SENP3 was required for B. abortus to multiply efficiently inside cells." (PMID 36609656, 2023). "Knockdown of PELP1 or SENP3 was reported to decrease HSV-1 titers, and PELP1 was found enriched with chromatin during HSV-1 infection at 8 hpi relative to mock infection." (PMID 31337724, 2019). "Analysis of the level of SENP3 retained in the nucleoli during infection showed a significant lack of nucleolar localisation of SENP3 in cells infected with the wild-type B. abortus strain in contrast with the ∆nyxA strain." (PMID 36609656, 2023). "At 48 h post-infection, wild-type infected cells showed a very high number of Bif in the absence of SENP3, with some cells containing more than 100 puncta." (PMID 36609656, 2023). "We observed a reduction in the percentage of cells with more than 10 bacteria at 48 h post-infection when SENP3 was depleted but not at earlier stages." (PMID 36609656, 2023).
infection (continued). "Importantly, depletion of SENP3 alone was insufficient to induce NVL cytoplasmic accumulation, suggesting this phenotype is triggered by the infection." (PMID 36609656, 2023). "The results showed that the SENP3 expression levels were not visibly changed from 6 h to 18 h post-PCV2 infection, but significantly upregulated at 24 h post-PCV2 infection, compared with the mock infection." (PMID 38394330, 2024).
cardiovascular diseases (3 papers, 2020 to 2025). "SENP3 plays critical roles in the regulation of various cellular activities, and the variation of the SENP3 expression level is closely related to various diseases, including the occurrence and development of tumors, cardiovascular diseases, and neurological diseases." (PMID 33192553, 2020).
SENP3 also shares sentences with these, for which no sentence is quoted: triple-negative breast carcinoma (4 papers); injury (3); neurological diseases (2); acute myeloblastic leukemia (1); Alzheimer disease (1); aneurysm (1); brain ischemia (1); cerebral infarct (1); colorectal cancer (1); dementia (1); Down syndrome (1); gastrointestinal disease (1); heart disease (1); infarct (1); malaria (1); Non-Alcoholic Fatty Liver Disease (1); non-small cell lung carcinoma (1); ovarian tumor (1); pancreatic ductal adenocarcinoma (1); rectal cancer (1); sarcoma (1).